CFTR (CF transmembrane conductance regulator)
Diseases named in the same sentence as CFTR in open-access papers (continued):
Sharing a sentence is not in itself a finding about the gene and the disease.
cystic fibrosis (continued). "The previous conclusion that PDE inhibitors are ineffective in restoring CFTR-dependent ion transport in cystic fibrosis mutated cells was challenged by a recent study that demonstrated selective PDE4 inhibitor-associated amplification in the CFTR correctors and/or CFTR potentiators." (PMID 36017299, 2022). "Cystic Fibrosis is an autosomal recessive disease caused by mutations in the gene encoding for the cystic fibrosis transmembrane conductance regulator (CFTR), a 1480 aa cAMP- regulated Cl- channel expressed at the apical membrane of epithelial cells in the airways and in other tissues." (PMID 34198675, 2021). "When both copies of the CFTR gene are mutated, patients are affected by cystic fibrosis, a genetic disease characterized by high viscosity of secreted fluids and by an abnormal inflammatory response, independent but aggravated by infections, leading to respiratory failure and premature death." (PMID 34203982, 2021). "In the cystic fibrosis lung, due to genetic mutations in the cystic fibrosis transmembrane regulator (CFTR) ion channel responsible for this disease, the mucus lining of the airways becomes dehydrated and highly viscous, leading to impaired clearance and accumulation." (PMID 33658597, 2021). "Cystic Fibrosis is a life-shorting rare genetic disorder affecting 90,000 to 100,000 individuals worldwide, that results from over 2,100 variants in the CF transmembrane conductance regulator (CFTR) gene." (PMID 34782688, 2021). "Cystic Fibrosis is a rare genetic disease caused by mutations in a gene called the CF Transmembrane conductance Regulator (CFTR), which codes for a chloride and bicarbonate transport protein located on the surface of epithelial cells in organs throughout the body." (PMID 34063507, 2021). "Cystic fibrosis is an autosomal recessive disease caused by dysfunctional cystic fibrosis transmembrane conductance regulator (CFTR) protein, and is marked by an accumulation of mucus in affected airways resulting in persistent infection and chronic inflammation." (PMID 34475490, 2021). "The defective mucociliary clearance due to CFTR malfunctioning causes predisposition to the colonization of pathogens responsible for the recurrent inflammation and rapid deterioration of lung function in patients with cystic fibrosis." (PMID 33513903, 2021). "However, since 2012, different combinations of CFTR modulators are available for people with cystic fibrosis (pwCF) that carry different mutations." (PMID 34213646, 2021). "The most common CFTR pathogenetic variant associated with cystic fibrosis is p.Phe508del (F508del)." (PMID 33407736, 2021). "Cystic fibrosis is the most frequent lethal inherited disease in the Caucasian population and is caused by a defective cystic fibrosis transmembrane conductance regulator gene (CFTR)." (PMID 34025651, 2021). "Pathogenic variants of the Cystic Fibrosis Transmembrane conductance Regulator (CFTR) gene, by lowering or abolishing the CFTR Cl- channel activity, cause a broad spectrum of clinical manifestations spanning from Cystic Fibrosis to the so-called CFTR related disorders (CFTR-RD)." (PMID 33916525, 2021). "The presence of mutation in the ABCC7/CFTR gene has been associated with cystic fibrosis which is a prevalent disease in white populations; dysfunction and changes in gene expression have been implicated in other disease development, including chronic inflammation." (PMID 34512749, 2021). "Cystic fibrosis, one of the most prevalent life-threatening monogenetic diseases, is caused by loss-of-function mutations in the CF transmembrane conductance regulator (CFTR) gene." (PMID 34357110, 2021). "Particularly common pathogenic variants have been observed in certain other genetic diseases: e.g. p.Phe508del variant in CFTR in cystic fibrosis in Europeans, population-specific variants in HFE in hemochromatosis, and population-specific truncating variants in GJB2 in deafness." (PMID 33736665, 2021).
cystic fibrosis (continued). "For instance, in the case of cystic fibrosis, an autosomal recessive disorder caused by the dysfunction of the CFTR gene, 28% of living human cystic fibrosis airway epithelial cells (CuFi-1) were transfected with the pEGFP reporter plasmid, using a lipid-based non-viral vector, named as N3." (PMID 34299164, 2021). "Cystic fibrosis is the most common autosomal recessive disorder in Caucasian populations caused by mutations in the cystic fibrosis transmembrane conductance regulator (CFTR) gene." (PMID 33924887, 2021). "However, in some cases chaperones “inappropriately” sequester otherwise functional proteins, such as the ΔF508 mutant allele of CFTR, the most common mutation causing human cystic fibrosis." (PMID 34544131, 2021). "On the other hand, over 1000 sequence variants in the CFTR gene can cause cystic fibrosis." (PMID 34071827, 2021). "Cystic fibrosis is caused by loss of function of the CFTR chloride channel." (PMID 34769402, 2021). "Cystic fibrosis, is an autosomal recessive disease that is caused by mutations in the CFTR gene." (PMID 34513358, 2021). "SERPINA1 gene, encoding AAT protein, is known as a modifying gene of cystic fibrosis whereby our data allow speculating that AAT may facilitate CFTR-mediated epithelial fluid secretion and improve mucociliary clearance." (PMID 33946490, 2021). "Cystic fibrosis is caused by pathogenic mutations in a single large gene located on human chromosome 7 that encodes the cystic fibrosis transmembrane conductance regulator (CFTR) protein." (PMID 34557648, 2021). "To date, over 1000 mutations of the CFTR gene that causes cystic fibrosis have been discovered." (PMID 34513358, 2021). "It is possible that deficiencies in CFTR function, such as those observed in cystic fibrosis, could dampen bitter agonist-mediated changes in epithelial current." (PMID 33509163, 2021). "Carriers of some genetic variants of the Cystic Fibrosis Transmembrane Conductance Regulator (CFTR) may present with cystic fibrosis associated with ASD, probably because CFTR may be a positive regulator of NKCC1." (PMID 34439564, 2021). "Loss-of-function mutations of the cystic fibrosis transmembrane conductance regulator (CFTR) anion channel disrupt transepithelial salt-water transport in the lung, intestine, pancreatic duct, and sweat duct, and cause cystic fibrosis, the most common inherited lethal disease among caucasians." (PMID 34870594, 2021). "Cystic fibrosis is a common monogenic disease caused by pathogenic variants in the CFTR gene." (PMID 34220950, 2021). "Screening for CFTR mutations in infertile men is carried out after identification of congenital absence of the vas deferens, since mutations in the CFTR gene can cause both a severe hereditary disease of cystic fibrosis and aplasia of the vas deferens." (PMID 34290736, 2021). "Thus, ABCC7 is the ATP-gated chloride channel cystic fibrosis transmembrane conductance regulator (CFTR) with inactivating mutations causing cystic fibrosis, and ABCC8 and ABCC9 are regulatory subunits of complex potassium channels." (PMID 34199119, 2021). "Cystic fibrosis is a genetic disorder, which is caused by the CFTR protein defects." (PMID 33879218, 2021). "Similarly, cystic fibrosis causing mutations in the channel protein CFTR (cystic fibrosis transmembrane conductance regulator) shows the alleviation of phenotype when the mutant protein is dissociated from its cognate chaperone Aha1131,132." (PMID 34632458, 2021). "Thanks to the support of the European Cystic Fibrosis Society we could recruit and examine monozygotic twins with cystic fibrosis who are homozygous for the most common disease-causing CFTR mutation p.Phe508del." (PMID 33708199, 2021).
cystic fibrosis (continued). "The Cystic Fibrosis Transmembrane Conductance Regulator (CFTR) gene variant, c.3453G > C (D1152H), is associated with mild Cystic Fibrosis disease, though there is considerable clinical variability ranging from no detectable symptoms to lung disease with early acquisition of Pseudomonas aeruginosa." (PMID 32414100, 2020). "Ten cystic fibrosis subjects homozygous for the F508del CFTR mutation participated in this study." (PMID 32616918, 2020). "For example, cystic fibrosis is a disease that may result from any one mutation of more than 1000 described variants in the CFTR gene." (PMID 33987515, 2020). "Cystic fibrosis is an autosomal recessive condition caused by pathogenic genetic variants that compromise the function of the cystic fibrosis conductance transmembrane regulator (CFTR) gene product." (PMID 32384684, 2020). "The histologic changes—accumulation of insoluble eosinophilic material and inflammation—were reminiscent of chronic pancreatitis secondary to cystic fibrosis, a genetic disorder caused by mutations in the cystic fibrosis transmembrane conductance regulator (CFTR) gene." (PMID 32541668, 2020). "Such defects have been described in several disease-associated mutations in membrane proteins, such as cystic fibrosis transmembrane conductance regulator (CFTR) in cystic fibrosis and bile salt export pump (BSEP) in progressive familial intrahepatic cholestasis type 2." (PMID 32873342, 2020). "Cystic fibrosis is an autosomal recessive genetic disorder that results from the functional deficiency in a plasma membrane anion channel known as the cystic fibrosis transmembrane conductance regulator (CFTR)." (PMID 33291847, 2020). "In addition to their pharmacogenetic importance, genetic variation in 21 ABC transporters can cause congenital diseases, the most common of which is cystic fibrosis (OMIM 219700) caused by variants in ABCC7 (CFTR)." (PMID 32206879, 2020). "Moreover, Noone and Knowles (2001) characterized cystic fibrosis as a recessive genetic disease caused by mutations on both CFTR alleles." (PMID 32722328, 2020). "Finally, we generated an mRNA reporter encoding human CFTR mRNA containing the ΔF508 mutation, the most common causative allele for cystic fibrosis." (PMID 32053646, 2020). "Cystic Fibrosis is the most common life-shortening genetic disease among Caucasians, resulting from mutations in the gene encoding the Cystic Fibrosis Transmembrane conductance Regulator (CFTR)." (PMID 32313074, 2020). "Mutations within CFTR lead to cystic fibrosis and cystic fibrosis related liver disease (CFRLD)." (PMID 32432119, 2020). "One of the most recently described familial CRC syndromes involves individuals with cystic fibrosis caused by biallelic inactivating mutations in the cystic fibrosis transmembrane conductance regulator (CFTR) gene, who are highly susceptible to early, aggressive colorectal tumor development." (PMID 32326161, 2020). "Cystic Fibrosis, a life-threatening recessive disorder affecting ~80,000 individuals worldwide, is caused by mutations in the gene encoding the CF transmembrane conductance regulator (CFTR) protein present at the apical membrane of epithelial cells." (PMID 32630527, 2020). "Cystic fibrosis is an autosomal recessive disorder that affects 1 out of 2500 newborns among Caucasians and it is caused by mutations in the gene encoding the cystic fibrosis transmembrane conductance regulator (CFTR) protein." (PMID 32751630, 2020). "Indeed, G3BP1 was recently described to promote proteasomal function and inhibit accumulation of ubiquitinated protein aggregates associated with Parkinson’s (α-synuclein) and Cystic Fibrosis (CFTR-ΔF508), which were induced by p62 and USP10." (PMID 32992901, 2020). "Cystic fibrosis is a life-long inherited disease that affects >70,000 patients globally; it is caused by underlying genetic mutations in the cystic fibrosis transmembrane conductance regulator (CFTR) gene." (PMID 32443586, 2020).
cystic fibrosis (continued). "In 2002, Ma TH found that thiazolidinone CFTR inhibitors may be useful in developing large-animal models of cystic fibrosis and in reducing intestinal fluid loss in cholera and other secretory diarrheas." (PMID 33103563, 2020). "Of note, as cystic fibrosis is a monogenetic disease characterized by mutations in the Cystic Fibrosis Transmembrane Conductance Regulator (CFTR), one could speculate that host genetics plays a role in the secretion and content of EVs." (PMID 32850874, 2020). "It is interesting to note that the idea of using PCs or PRs emerged from an early observation where ΔF508 CFTR, a single phenylalanine deletion mutant found in more than 85% of cystic fibrosis alleles was functional when expressed in Xenopus oocyte grown at room temperature." (PMID 33173538, 2020). "Indeed, both E3 ligases have been implicated in ERAD of a misfolded version of the cystic fibrosis transmembrane conductance regulator, CFTRΔF508, which is associated with cystic fibrosis." (PMID 33137101, 2020). "This sequence of events results from mutations in the CFTR gene and leads to cystic fibrosis." (PMID 32481719, 2020). "Pathogenic variants in CFTR decrease ion channel function and cause extracellular mucus build-up; excessively thick and sticky mucus obstructs airways and pancreatic ducts, resulting in cystic fibrosis." (PMID 32425982, 2020). "Concerning cystic fibrosis, an inverse relationship between the two is well demonstrated; indeed, chronic inflammation of the lung, which is a key element of the disease, is strictly linked to the upregulation of NFκB that is found when CFTR is mutated." (PMID 32046116, 2020). "Cystic fibrosis is an inherited genetic disease that affects over 70,000 people worldwide and is characterized by mutations in the cystic fibrosis transmembrane conductance regulator (CFTR)." (PMID 32576671, 2020). "Cystic Fibrosis, is an autosomal recessive life-limiting disease, characterised by viscid secretions in multiple organ systems due to mutations affecting the CFTR gene, which codes for a cAMP-regulated chloride channel, found on epithelial surfaces, including the airways, pancreas, and intestine." (PMID 33031374, 2020). "In genetic mutations, inactivating ENaC (systemic pseudohypoaldosteronism) or CFTR (cystic fibrosis), there are tenacious dehydrated airway secretions causing lung disease and this is the clinical picture found in COVID 19 patients regarding their airway secretions." (PMID 32922301, 2020). "Cystic fibrosis, a lethal hereditary disease caused by mutations in the cystic fibrosis transmembrane conductance regulator (CFTR) gene coding for an epithelial chloride channel, is characterized by an imbalanced homeostasis of ion and water transports in secretory epithelia." (PMID 32962254, 2020). "CFTR gene mutation can cause cystic fibrosis, chronic lung disease, and infertility." (PMID 33271827, 2020). "Cystic fibrosis patients have mutated CFTR and completely lack the ability to secrete HCO3−." (PMID 33291407, 2020). "The genetic reasons for cystic fibrosis are mutations in the CFTR gene on chromosome 7." (PMID 32722328, 2020). "Interestingly, autophagy can play a role also in the unconventional trafficking of the cystic fibrosis transmembrane conductance regulator (CFTR, the protein mutated in cystic fibrosis) from the ER to the plasma membrane, bypassing the Golgi52." (PMID 31729431, 2019). "Cystic fibrosis is an autosomal recessive genetic disorder characterized by poor chloride ion (Cl-) transport across cell membranes due to mutations in the cystic fibrosis transmembrane conductance (CFTR) gene." (PMID 30813317, 2019). "Cystic fibrosis is a chronic autosomal recessive disorder that affects the lungs and the digestive system of approximately 70,000 people worldwide and is caused by mutations in the cystic fibrosis transmembrane conductance regulator (CFTR) gene." (PMID 30642010, 2019).
cystic fibrosis (continued). "In cystic fibrosis, the most common disease-causing mutation is F508del, which causes not only intracellular retention and degradation of CFTR, but also defective channel gating and decreased membrane stability of the small amount that reaches the plasma membrane (PM)." (PMID 31231217, 2019). "Mutations in CFTR cause the life-shortening autosomal recessive disorder, cystic fibrosis." (PMID 31491720, 2019). "Considering the current evidence, there are clearly many unanswered questions regarding the role of CFTR in human sperm fertilization competence and undertaking detailed systematic studies using sperm from men with known cystic fibrosis mutations would be necessary to help answer them." (PMID 31665287, 2019). "Cystic fibrosis is a lethal autosomal recessive disorder caused by mutations in the CF Transmembrane Conductance Regulator (CFTR) gene encoding for a cAMP-activated anionic channel, secreting mainly chloride (Cl−) and bicarbonate (HCO3−) at the apical surface of epithelia." (PMID 31019198, 2019). "Finally, we treated a cystic fibrosis bronchial epithelial (CFBE) cell line harboring the most frequent CFTR mutation (delF508) for 24 h with SQ1 or SQ2 in the absence or presence of bafilomycin A1." (PMID 30858361, 2019). "Cystic fibrosis is uncommon among Japanese, so CFTR mutations were also thought to be rare." (PMID 30992994, 2019). "Cystic fibrosis is an autosomal recessive disease caused by mutations in the CFTR gene." (PMID 31391465, 2019). "This approach was recently tested by treating IB3.1 cells (a cystic fibrosis cell model harboring the W1282X stop mutation) with caffeine to increase levels of nonsense CFTR-mRNA to restore a functional protein produced by PTC suppression with Ataluren, thus providing a greater therapeutic benefit." (PMID 31284579, 2019). "Cystic fibrosis is a lethal genetic disorder caused by deleterious mutations in the CF transmembrane conductance regulator (CFTR) protein, resulting in compromised mucociliary clearance, chronic bacterial infections, and subsequent progressive inflammatory lung damage." (PMID 30759393, 2019). "Cystic fibrosis is caused by mutations in the CFTR gene, which are subdivided into six classes." (PMID 30659068, 2019). "Cystic fibrosis is the most common life-limiting genetic disorder within the Caucasian population, with 1 in 40 people estimated to carry the common ΔF508 mutation in the CF transmembrane conductance regulator (CFTR) gene." (PMID 31824471, 2019). "Cystic fibrosis is a common autosomal recessive disorder that affects the sweat glands and the digestive, respiratory, and reproductive systems due to genetic variants in the cystic fibrosis transmembrane conductance regulator (CFTR) gene." (PMID 33072991, 2019). "There are over 2000 mutations of the CFTR gene recorded in the Cystic Fibrosis Mutation Database." (PMID 29515516, 2018). "Specific mutations that either block the CFTR gene from being transcribed or affect the protein product in particular ways will cause loss of functionality, generating the clinical manifestations of cystic fibrosis." (PMID 29888417, 2018). "Macrophages from patients with cystic fibrosis, who have dysfunctional chloride currents due to mutations in the Cystic Fibrosis Transmembrane Conductance Regulator (CFTR) gene, are characterised by persistent pro-inflammatory activation and defective phagocytosis, facilitating chronic infection." (PMID 29973568, 2018). "Cystic Fibrosis is a life-threatening recessive genetic disorder resulting from mutations in the gene encoding the fibrosis transmembrane conductance regulator protein (CFTR)." (PMID 30627177, 2018). "These samples originated from cystic fibrosis patients with known CFTR mutation status." (PMID 29466940, 2018). "Cystic fibrosis is one of the most lethal autosomal-recessive diseases caused by mutation in CFTR." (PMID 30319426, 2018).